TNF (tumor necrosis factor)
Diseases named in the same sentence as TNF in open-access papers (continued):
Sharing a sentence is not in itself a finding about the gene and the disease.
Infertility (continued). "The connection between UFs and infertility, together with the potential impact of TNF-α in this regard, should be highlighted." (PMID 30518097, 2018). "EAO is characterized by leukocytic infiltrates in the interstitium, damage of spermatogenesis and production of inflammatory mediators like TNFα and MCP1 causing infertility." (PMID 29487346, 2018). "Second, a negative impact of TNF-alpha was observed on spermatozoa motility and TNF-blocking therapies are currently under study for the treatment of infertility." (PMID 28085963, 2017). "The effect of TNFα on testosteroneproduction, which has a direct impact onmale infertility, has also been reported in some experimentalmodels." (PMID 28670429, 2017). "Aside from this, cytokines such as IL-1, IL-6, and tumor necrosis factor (TNF) can lessen sperm motility and decrease the likelihood of sperm reaching the ovum, further contributing to infertility in males." (PMID 28515223, 2017). "T cell-derived TNF-alpha signaling was required for chlamydial-induced infertility and caspase inhibitors prevented both infertility and EMT." (PMID 26681200, 2015). "The production of TNF-α and IL-10 was examined because their levels have been reported to be high in cervical secretions of C. trachomatis infected infertile women." (PMID 18489796, 2008). "A significant cHSP60 specific increase in TNF-alpha levels (P = 0.0008) was observed in infertile group as compared to fertile group." (PMID 18489796, 2008). "We also evaluated IFN-γ and TNF-α levels and higher levels of both the cytokines were detected in infertility group after stimulation with cHSP60 and cHSP10." (PMID 18489796, 2008). "In men, higher levels of IL-1, IL-6, and TNF were detected in those with infertility." (PMID 40933264, 2025). "Additionally, chronic low-grade inflammation increases pro-inflammatory cytokines like TNF-α and IL-6, which can damage the uterine microenvironment and impair ovarian function, contributing to infertility." (PMID 39815248, 2025). "Considering that TNF-alpha mRNA is present at greater levels in the seminal plasma of infertile men and interferes with embryo development, THC-induced reductions in sperm miR-324 may influence the abundance of this cytokine in sperm and embryos." (PMID 38536780, 2024). "TNF-α regulates spermatogenesis and has been reported to be increased unexplained infertility." (PMID 37027384, 2023). "TNF-α was found to be increased in infertile males in the present study." (PMID 37027384, 2023). "Indeed, FF levels of TNF-α and IL-6 were found to be higher in infertile women with PCOS compared to control women." (PMID 37493841, 2023). "We assessed the potential role of proinflammatory cytokines (TNF-α, IL-6 and IL-1α) and microRNAs (miR-146a-5p, miR-34a-5p and miR-23a-3p) in the seminal plasma of infertile men compared to controls, evaluating their correlation with seminal and biochemical parameters." (PMID 34319544, 2021). "Moreover, other pro-inflammatory cytokines, such as IL-6, IL-1β, and tumor necrosis factor-alpha (TNF-α), were largely investigated both in blood and in semen samples of infertile males, providing contradictory results." (PMID 33806677, 2021). "Examination of a model of autoimmune orchitis (chronic inflammation and infertility) suggested that increasing the content of TNF-α may induce apoptosis of sperm." (PMID 32610645, 2020). "Many studies have shown that TNF-α inhibitors improve infertility treatment outcomes." (PMID 33269158, 2020). "TNF-α seems to play a role in the pathogenesis of varicocele probably inducing sperm apoptosis, which, also in this study, was significantly increased in both groups of infertile patients with respect to controls." (PMID 31781347, 2019). "Furthermore, infertile heifers had significantly higher expression of TNFα, IL-6, and CXCL5 in their white blood cells." (PMID 30181662, 2018).
Infertility (continued). "Moreover, unexplained infertile patients have demonstrated elevated levels of serum IL-2, IL-4, IL-6, IL-21, tumor necrosis factor alpha (TNF-α), and IFN-γ, compared with fertile women." (PMID 30546347, 2018). "Mechanistically, increased TNF-α secretion led to RPL through inducing trophoblast invasion and placentation and proapoptotic gene expression in human fetal membranes, resulting in accelerated membrane degradation and increased infertile susceptibility." (PMID 26837816, 2016). "This situation remindsus a question whether the success rates ofIVF applications in infertile women can be increasedby use of TNF-α blockers." (PMID 26644849, 2015). "The requirement for T cells, the T cell-derived cytokine TNF-alpha and caspase-3 for chlamydial-induced infertility and tubal pathologies suggested that the pathogenesis of chlamydial reproductive complications involved TNF-alpha signaling and caspase activation." (PMID 26681200, 2015). "TNF-α in IVF has already been the subject of much study by infertility researchers." (PMID 22007253, 2012). "Further, along with IFN-γ, TNF-α is reported to have implications in infertility." (PMID 19397832, 2009). "Notably, significantly elevated concentrations of TNF-alpha in granulosa cell cultures from women with EMS have been reported, which may also be linked to infertility." (PMID 38002087, 2023). "Therefore, TNF inhibitors have certain application value in IVF-ET in infertile women with PCOS." (PMID 37055769, 2023). "Moreover, we have also demonstrated that ISO-induced oxidative stress generates inflammation via the upregulation of MPO, TNF-α, and IL-6, which should also contribute to the reduction in testosterone concentrations and the reduced ratio of mature sperm, leading to infertility." (PMID 35326087, 2022). "Furthermore, TNF-α is closely related to tubal inflammatory injury and infertility." (PMID 34754312, 2021). "If safe drug connections were found, a broader spectrum of symptoms could be better eliminated, e.g., one drug decreases TGF-β3 levels and slows down the ECM formation, whereas another drug decreases TNF-α level and has a beneficial effect on pain and infertility." (PMID 30518097, 2018). "Hence from the present study higher levels of both IFN-γ and TNF-α by cHSPs in infertility group may suggest their involvement in the immunopathological condition associated with the infertility." (PMID 18489796, 2008). "Network pharmacology identified linoleic acid, oleic acid, biotin, and esculentic acid as key contributors to the extract's anti-infertility effects, potentially via interactions with EGFR, HIF1, BCL2, TNF, and AKT1." (PMID 42199843, 2026). "Cytokines like interleukin 1β (IL-1β), IL-6, IL-10, IL-18, tumor necrosis factor α (TNF-α), interferon g (IFN-g), and transforming growth factor β1 (TGF-β1) are notably elevated in idiopathically infertile males and those with varicocele." (PMID 40070583, 2025). "Winger has found that the use of TNF-alpha inhibitors and intravenous immunoglobulin (IVIG) significantly improves in vitro fertilization (IVF) outcome in young infertile women withTh1/Th2 cytokine elevation." (PMID 36750949, 2023). "A significant reverse correlation was seen between recurrent abortion and TNF-⍺ and IFN-γ genes expression in sperm cells of infertile men before treatment (r = −0.41, r = −0.39 and p=0.004, p=0.01, respectively)." (PMID 35360193, 2022). "The objective of this study was to measure gamma interferon (IFN-γ) and tumor necrosis factor alpha (TNF-α) expression in endometrial tissue and/or aspirate from suspected genital tuberculosis patients with ectopic pregnancy and infertility in Bangladesh." (PMID 35198736, 2022). "• Circulating levels of OPN, CD44 and inflammatory cytokines TNF-α and IFN-γ are altered in infertile PCOS patients." (PMID 33047155, 2020). "The NC in infertile men significantly increased total antioxidant capacity and reduced CRP and TNF-α levels." (PMID 30705687, 2019).
Infertility (continued). "This confirms our recent demonstration of the role of TNF-α in chlamydial pathogenesis in the mouse model, and is supported by evidence of a role of TNF-α in chlamydial pathologies in Chlamydia-induced infertility in humans." (PMID 23483844, 2013). "Significantly high levels of TNF-α and IL-6 levels were secreted in CD4+ T cells from CT-positive fertile and infertile women compared to controls." (PMID 19698128, 2009). "Recent studies have shown that immunocompetent cells in the blood of PCOS patients with infertility in vitro produce several cytokines, including IFN-γ, TNF-α, and IL-2, which may be involved in chronic inflammation." (PMID 38911246, 2024). "The PDE4 inhibitor rolipram and the different pathways such as IL-6/NF-κB/TNFα/MAPK and cAMP/AQP5 mediating its effects against ovarian torsion damage may be a promising target for ovarian damage or infertility." (PMID 38453769, 2024). "Conversely, interferon-γ and tumor necrosis factor-α were decreased in ART, which might explain the more inflexible status related to adverse neonatal outcomes in newborns exposed to both infertility treatment and CAM." (PMID 37210503, 2023). "Recent studies have shown that several cytokines, including IFN-γ, TNF-α, IL-2, IL-4, IL-5, and IL-10, were produced by immunocompetent cells in the blood from PCOS with infertility in vitro, which might be involved in chronic inflammation." (PMID 30988342, 2019). "IL-6 and TNF-α were higher in the infertile group but they were not statistically significant." (PMID 37027384, 2023). "Unlike the effect on EMS, the inhibition of TNF-α did not appear to affect infertility." (PMID 38002087, 2023). "UC-MSCs also emerged to be beneficial in the revival of infertility in a mouse model of PCOS induced by dehydroepiandrosterone via inactivation of proinflammatory cytokines, for instance, IL- 1β, tumor necrosis factor alpha (TNFα), and interferon gamma (IFN-γ)." (PMID 34203240, 2021). "Moreover, infertile patients with leukocytospermia or varicocele showed significantly reduced seminal concentrations of obestatin and ghrelin concomitant with increased levels of CAT, MDA, IL-6, and TNF-α with respect to those observed in the control group." (PMID 31781347, 2019). "A recent study showed that using TNF-α inhibitor and intravenous immunoglobulin significantly improved the outcomes of IVF including; implantation, clinical pregnancy and live birth rates in young infertile women who had high levels of T helper 1/T helper 2 cytokines." (PMID 30546347, 2018). "Based on the results of this study, the lowest TNF-α expression was in the T2 group, which received the highest forest honey therapy (50% v/v), whereas the highest TNF-α expression was found in the infertile rat group without honey (T+)." (PMID 37767071, 2022). "Our study supported that chromium administration for 8 weeks significantly decreased gene expression of IL-1 and serum hs-CRP levels in infertile women with PCOS who were candidate for IVF, though it did not affect gene expression of IL-8, TNF-α, TGF-β, and VEGF." (PMID 30546347, 2018).
vitiligo (117 papers, 2011 to 2026). Generalized well circumscribed patches of leukoderma that are generally distributed over symmetric body locations and is due to autoimmune destruction of melanocytes. "Among anti-TNF drugs, patients treated with etanercept had the highest risk of developing vitiligo, followed by infliximab and adalimumab." (PMID 40861456, 2025). "Several cytokines implicated in vitiligo pathogenesis—including IL-17, IL-2, IL-6, IL-8, TNF-α, and IFN-γ—are regulated, at least in part, by vitamin D and its analogs." (PMID 41157208, 2025). "A 10-year cohort study indicated that patients receiving anti-TNF therapy had approximately twice the risk of developing vitiligo compared with those receiving conventional treatment." (PMID 40861456, 2025). "LEF administration demonstrated significant immunomodulatory capacity, reducing the serum levels of Th1-associated pro-inflammatory cytokines (IFN-γ, TNF-α, IL-2) while upregulating Th2-derived anti-inflammatory mediators (IL-4, IL-10) in vitiligo mice." (PMID 40725033, 2025). "The tumour necrosis factor (TNF) pathway has been of particular interest, with genetic mutations reported as risk factors for vitiligo in Egyptian38 and Saudi Arabian patients." (PMID 38312261, 2024). "TNF-α also plays a crucial role in the development of cytotoxic T lymphocytes implicated in the initiation of vitiligo, enhancing the release of IFN-γ, a cytokine directly involved in the depigmentation, exacerbating the local autoimmune response." (PMID 39063004, 2024). "While generally effective and safe, these therapies have been increasingly associated with secondary development of vitiligo, especially with anti-TNF α and anti-IL17 drugs." (PMID 39742272, 2024). "The expression of TNF-α is an essential key step of melanocyte dysfunction, which is disrupted in vitiligo, a chronic skin disorder characterized by loss of pigment-producing cells resulting in skin patches of depigmentation." (PMID 39063004, 2024). "Specifically, their findings indicated that TNF-α polymorphism significantly elevates the risk of vitiligo among Middle Eastern populations." (PMID 38850409, 2024). "TNF-α is associated with depigmentation, permanent phosphorylation of p38, and ROS increase in vitiligo." (PMID 39582871, 2024). "Our study also addresses some controversies in previous research, confirming a causal relationship between TNF and vitiligo, indirectly supporting the rationale for using TNF inhibitors in vitiligo treatment." (PMID 38660673, 2024). "Elevated serum TNFα was associated with AA and AG genotypes at −308 [rs1800629] in Iraqi and Chinese patients with vitiligo and congenital heart disease, respectively." (PMID 39055623, 2024). "A significantly increased risk of vitiligo was observed in the anti-TNF-α group compared to the unexposed group." (PMID 37175894, 2023). "Tumor necrosis factor (TNF)-α- 308 G/A gene polymorphism was the most investigated in vitiligo patients." (PMID 35905107, 2022). "We also found that the TNF-α-308A allele was significantly associated with vitiligo compared with HCs." (PMID 33370782, 2020). "This concurs with the results obtained from KSA, and Iran and with a meta-analytic study which reported that the TNF-α-308A allele was significantly associated with vitiligo in Middle Eastern populations." (PMID 33370782, 2020). "The current study aimed to measure the serum TNF-α (sTNF-α) level and the role of the SNP (rs1800629) as a risk for the susceptibility to AA and vitiligo among Egyptians, and to determine its correlation with duration and severity of these diseases." (PMID 33370782, 2020). "The current case-control study aimed to detect the sTNF-α level and the TNF-α-308(G/A) gene polymorphism in AA and vitiligo patients and to determine their relation with disease duration and severity." (PMID 33370782, 2020). "Previous studies have examined the potential contributions of the TNF-α-308 G/A polymorphism to the susceptibility to AA and vitiligo." (PMID 33370782, 2020).
vitiligo (continued). "Analysis of the association between TNF-α-308 G/A polymorphism and susceptibility to alopecia areata and vitiligo." (PMID 33370782, 2020). "T‐cell activation was analyzed by the increased expression of the activation marker CD137 and by the production of cytokines TNFα and IFNγ, which are associated with a type 1 T‐cell response often observed in vitiligo." (PMID 30767390, 2019). "Some (but not all) studies previously published have shown an increase in tumor necrosis factor (TNF)-α associated with vitiligo." (PMID 27635239, 2016). "Further, in vitro direct analysis of margins of vitiliginous skin showed polarized type 1 T cells (CD4+ and particularly CD8+) that predominantly secrete IFN-γ and TNF-α cytokines that are associated with the destruction of melanocytes during active vitiligo." (PMID 26442157, 2015). "For the first time, we show that the promoter polymorphisms of the TNF-α gene influence the expression both at transcriptional as well as translational levels in vitiligo." (PMID 23284977, 2012). "The present study explores TNF-α promoter polymorphisms and correlates them with TNF-α transcript and protein levels in vitiligo patients and controls of Gujarat along with its effect on disease onset and progression." (PMID 23284977, 2012). "Here, we report that TNF-α −238, −308, −857, −863 and −1031 promoter polymorphisms are significantly associated with Gujarat vitiligo patients." (PMID 23284977, 2012). "The LD analysis revealed that the five promoter polymorphisms investigated in the TNF-α gene were in low to moderate LD association in both generalized as well as localized vitiligo patients." (PMID 23284977, 2012). "The up-regulation of TNF-α transcript and protein levels in individuals with susceptible haplotypes advocates the crucial role of TNF-α in autoimmune pathogenesis of vitiligo." (PMID 23284977, 2012). "The role of TNF-α in vitiligo is quite controversial, but meta-analyses suggest the genetic predisposition to vitiligo in specific populations to be associated with specific TNF-α polymorphisms, reinforcing the role of TNF-α in disease susceptibility and immune dysregulation." (PMID 40430113, 2025). "Additionally, TNF-α-308 G/A polymorphism has been linked to a genetic susceptibility to vitiligo, particularly in specific populations, reinforcing the role of TNF-α in immune dysregulation." (PMID 40430113, 2025). "While TNF-α inhibitors can stabilize progressive vitiligo in some patients, they may also be associated with new-onset vitiligo in others." (PMID 39201060, 2024). "In addition, elevated serum TNFα levels have been associated with vitiligo in Iraqi41 and Iranian patients." (PMID 38312261, 2024). "The underlying mechanism of anti-TNF α agents-induced vitiligo may involve local changes in cytokine balance and the activation of alternative pathways such as type I interferon." (PMID 39742272, 2024). "While notable GWAS with smaller samples than ours have included those associating genetic variants with vitiligo and response to anti-tumor necrosis factor (anti-TNF) treatment, a larger sample would have enabled us to detect associations with smaller effect sizes." (PMID 35254093, 2022). "The pathogenesis of these might be linked to cytokines which also play a role in vitiligo pathogenesis, such as IL-1, IL-6, TNF-α, and possibly IL-17." (PMID 34445526, 2021). "Since various effector cytokines and cytolytic molecules have been shown to contribute toward melanocyte destruction, we developed the h3T-A2 transgenic mouse with deficiency for either IFN-γ, TNF-α, or perforin to understand the role of these molecules in vitiligo development." (PMID 24586745, 2014). "Moreover, imiquimod can induce cytokines such as IFN-α, TNF-α, IL-6, IL-8, and nitric oxide to cause vitiligo." (PMID 24928346, 2014). "Also TNF-alpha genotype polymorphism (GA genotype was significantly higher in vitiligo patients) has been associated with an increased risk of vitiligo in Saudi patients." (PMID 24665368, 2014).